RNF215 (ring finger protein 215)
Tractability: Antibody: UniProt predicts a signal peptide or a membrane-spanning region. PROTAC: ubiquitination databases record sites on it.
Gene: Protein-coding gene on chromosome 22 (30,368,811 to 30,421,771, reverse strand). Ensembl gene ENSG00000099999.
Subcellular location: Membrane
Subcellular location (Human Protein Atlas): Microtubules; Nucleoli
Gene Ontology:
Molecular function: ubiquitin protein ligase activity
Biological process: ubiquitin-dependent protein catabolic process
Cellular component: membrane
Genetic constraint (gnomAD): Loss-of-function variants: 39 observed, 40.34 expected, observed/expected ratio (o/e) 0.97, 90% interval 0.75 to 1.26. The upper end of that interval is the gene's LOEUF score, 1.26, which puts it in group 5 of 6, group 1 being the genes least tolerant of losing a copy. Missense variants: 377 observed, 393.38 expected, observed/expected ratio (o/e) 0.96, 90% interval 0.88 to 1.04. Synonymous variants: 176 observed, 172.21 expected, observed/expected ratio (o/e) 1.02, 90% interval 0.9 to 1.16.
Homologues: Orthologues: chimpanzee RNF215 (99% identical), macaque RNF215 (98% identical), dog RNF215 (95% identical), guinea pig RNF215 (92% identical), rat Rnf215 (92% identical), pig RNF215 (92% identical), mouse Rnf215 (90% identical), rabbit RNF215 (56% identical), zebrafish rnf215 (37% identical), Drosophila melanogaster gzl (14% identical), Caenorhabditis elegans C18B12.4 (13% identical). Paralogues in human: RNF130 (18% identical), RNF149 (18% identical), RNF150 (18% identical), RNF128 (15% identical), RNF133 (14% identical), RNF148 (13% identical), RNF13 (12% identical), RNF167 (12% identical), ZNRF4 (12% identical).
Diseases named in the same sentence as RNF215 in open-access papers:
RNF215 is named in the same sentence as 6 diseases in open-access papers, as found by Europe PMC text mining. Sharing a sentence is not in itself a finding about the gene and the disease. The quoted sentences say what the papers report.
head and neck squamous cell carcinoma (2 papers, 2022 to 2023). A squamous cell carcinoma that arises from any of the following anatomic sites: lip and oral cavity, nasal cavity, paranasal sinuses, pharynx, larynx, and salivary glands. "In addition, RNF215 is introduced within a four−gene methylation signature to predict the survival outcome of head and neck squamous cell carcinoma." (PMID 37671061, 2023). "However, a study in head and neck squamous cell carcinoma described a characteristic promoter methylation pattern of ZNF10, TMPRSS12, ERGIC2, and RNF215 genes, which was proposed as a biomarker of response to radiotherapy treatment." (PMID 35359376, 2022).
viral infection (2 papers, 2023 to 2025). "RNF215 expression is only reported to be upregulated by viral infection in human macrophages and might play an important role in the pathogenesis of autoimmune diseases." (PMID 37671061, 2023). "For example, RNF5, RNF122, and RNF215 have been shown to negatively regulate NF-κB-, RIG-I-, or STING-mediated IFN responses during viral infection." (PMID 40261845, 2025).
cancer (1 paper, 2020). A tumor composed of atypical neoplastic, often pleomorphic cells that invade other tissues. "Our rnf185 and rnf215 zebrafish mutants may be used for cancer genetic studies in the future." (PMID 31915253, 2020).
RNF215 also shares sentences with these, for which no sentence is quoted: autoimmune disease (1 paper); colorectal cancer (1); sarcoidosis (1).